EDN1 (endothelin 1)
Diseases named in the same sentence as EDN1 in open-access papers (continued):
Sharing a sentence is not in itself a finding about the gene and the disease.
preeclampsia (62 papers, 2009 to 2025). Preeclampsia is a hypertensive disorder of pregnancy that is characterized by new-onset hypertension with proteinuria presenting after 20 weeks of gestation, and depending on mild or severe forms may initially present with severe headache, visual disturbances, and hyperreflexia. "Many of the hormones implicated in preeclampsia, including angiotensin II, vasopressin, and endothelin-1 signal through GPCRs, and their associated cascades can influence the distribution and activity of class IIa HDACs." (PMID 41416997, 2025). "Reduced uteroplacental perfusion, the initiating event in preeclampsia, is associated with enhanced endothelin-1 (ET-1) production which feeds the vasoconstriction of uterine artery." (PMID 21298073, 2011). "Preeclampsia is associated with significantly increased levels of vasoconstrictor endothelin-1 (ET-1), anti-angiogenic factor sFlt-1, and inflammatory marker C-reactive protein (CRP) in the maternal circulation, which are thought to contribute to systemic vascular dysfunction." (PMID 35897759, 2022). "Treg cell depletion in mice causes increased uterine artery vasoconstriction and endothelin-1 production, suggesting that altered vasoreactivity in preeclampsia may relate to the reduction in Treg cells." (PMID 34831277, 2021). "miR-206 can down-regulate the expression of EDN1 gene, which may be related to the increased risk of preeclampsia." (PMID 32481405, 2020). "Mice (Edn1H/+) having excess endothelin-1 developed preeclampsia-like phenotypes during pregnancy in a maternal genotype-dependent manner." (PMID 41227291, 2025). "Mice treated with the handle region peptide (HRP), another (P)RR inhibitor, reduced maternal blood pressure and proteinuria, inhibited endothelin-1 production and improved fetal weights in a mouse model of preeclampsia (RUPP)." (PMID 38605139, 2024). "Studies have shown that patients with preeclampsia are characterized by elevated sFLT1, soluble endoglin, and endothelin-1 levels that are induced by elevated placental HIF-1 levels." (PMID 38678187, 2024). "During preeclampsia, patients have increased serum levels of vasoconstrictors such as endothelin 1 (ET-1) and thromboxane, while the responsiveness to vasodilators including nitric oxide (NO) and prostacyclin is significantly reduced in vivo." (PMID 37043045, 2023). "Such patients have also been observed to have higher endothelin-1 concentrations and a positive correlation between endothelin-1 concentrations and the severity of preeclampsia." (PMID 34884974, 2021). "In the context of preeclampsia, endothelin-1 is a powerful regulator of uterine artery resistance, which has a direct impact on uteroplacental perfusion." (PMID 34831277, 2021). "Hyperactive AT1R-B2R heteromers trigger enhanced down-stream effects such as the increased generation of vasoconstrictors and endothelin-1, which are elevated in preeclampsia, and the anti-angiogenic sFlt1, which is a major feature of preeclampsia." (PMID 34685589, 2021). "The podocyte damage mechanism in preeclampsia is connected to free VEGF and nitric oxide (NO) deficiency, and an increased concentration of endothelin-1 and oxidative stress." (PMID 32708979, 2020). "Endothelin-1 (ET-1) was reported to be crucial for preeclampsia pathogenesis and arterial pressure regulation." (PMID 32758232, 2020). "Increasing evidence suggests an important role for endothelin-1 (ET-1) in the pathophysiology of preeclampsia." (PMID 28264495, 2017). "Increasing evidence suggests that endothelin-1 plays an important role (ET-1) in the pathophysiology of preeclampsia." (PMID 28264495, 2017). "Endothelin-1 (ET-1) is a vasoconstrictor that is secreted from the endothelium into the circulation and has been shown to be elevated in the circulation of women with preeclampsia." (PMID 28500309, 2017).
preeclampsia (continued). "If perturbed endotheil-1 signaling and/or disruption of endothelin-1/NO balance are proven to be the final common pathway for induction of preeclampsia, this concept would have huge translational potential implications." (PMID 22848831, 2012). "Others found higher total VEGF (vascular endothelial growth factor), MMP-2, and endothelin-1 concentrations in umbilical vein endothelial cells of women with preeclampsia and showed significant positive correlations between them." (PMID 19698156, 2009). "Endothelin-1 (ET-1) is involved in the pathogenesis of preeclampsia." (PMID 41227291, 2025). "However, women with preeclampsia display heightened sensitivity to or secretion of angiotensin II and vasopressin, which are known to facilitate the release of endothelin-1, as well as decreased nitric oxide-dependent vasodilation." (PMID 41416997, 2025). "Here, we examined whether the proton pump inhibitor omeprazole could acutely reduce sFlt-1 and ET-1 (measured as CT-proET-1 [C-terminal pro-endothelin-1]), or increase free PlGF (placental growth factor) in 20 women with confirmed preeclampsia." (PMID 35341328, 2022). "Increased circulating endothelin-1 levels contribute to preeclampsia symptoms and hypertension." (PMID 34685589, 2021). "In addition to vasodilatory substances such as nitric oxide, the vasoconstrictive peptides angiotensin II and endothelin-1 also play a role in the symptomology of preeclampsia." (PMID 34831277, 2021). "Angiotensin II, endothelin-1, and other vasoconstrictive hormones, including vasopressin, predominantly signal through G protein-coupled receptors (GPCRs), and excess input from these substances has been attributed to the symptomology of preeclampsia." (PMID 34831277, 2021). "Moreover, AT1-AA along with circulating cytokines stimulate endothelial cells to produce endothelin-1 (ET-1) in preeclampsia, which is a major endothelium-derived vasoconstrictor." (PMID 34681861, 2021). "By enhancement of AT1R-B2R-mediated signaling, mechano-stimulation of AT1R-B2R by the growing fetus could also actively promote an increase in the preeclampsia-related anti-angiogenic sFlt1 and vasoactive endothelin-1." (PMID 34685589, 2021). "Endothelin-1 (ET-1) is a potent vasoconstrictor elevated in preeclampsia." (PMID 29466360, 2018). "Cardiac gene expression of Vcam, Edn1, Ccr2, Ctgf, Tgfb1, Tgfb2, Tgfb3, Bnp, Cybb, Mmp2, Mmp9, Timp1, Camk2a, Slc9a1, Nr3c2, and Nr3c1 was not different between mice who had a normal pregnancy and mice who had a preeclampsia-like pregnancy at 5 or 10 weeks postpartum (respectively)." (PMID 40425613, 2025). "In the present study, we performed a randomized controlled trial to evaluate whether omeprazole treatment could alter the circulating and cord blood levels of sFlt-1, PlGF and CT-proET-1 (C-terminal pro-endothelin-1; a stable surrogate marker of ET-18) in women with confirmed preeclampsia." (PMID 35341328, 2022). "Previous studies showed that women with preeclampsia had persistent elevated placental HIF-1α levels that enhanced the transcription of genes that encoded soluble fms-like tyrosine kinase-1 (sFlt-1), soluble endoglin (sEng), and endothelin-1 (ET-1), all known to contribute to preeclampsia." (PMID 33758274, 2021). "Additionally, it has been reported that CO derived from HO-1 in vascular smooth muscle could inhibit production of endothelin-1, a protein shown to be a final common pathological factor in several experimental models of preeclampsia." (PMID 22195275, 2012). "There is growing evidence supporting the role of the endothelin 1 (EDN) axis in female reproductive disorders, such as endometriosis, preeclampsia, and ovarian and cervical cancer." (PMID 37109658, 2023). "Changes in other hormones (e.g., ANP, BNP, epinephrine, and endothelin-1) with position were not different between pregnancies with preeclampsia, normotensive pregnancies, and non-pregnant controls." (PMID 39100275, 2024).
preeclampsia (continued). "The cause of decreased estrogen in preeclampsia has not been directly identified but may be a result of elevated reactive oxygen species due to angiotensin II type 1 receptor autoantibodies (AT1AA), endothelin-1, vasopressin, or hypoxia." (PMID 41416997, 2025).
Sepsis (62 papers, 2005 to 2026). Sepsis is defined as life-threatening organ dysfunction caused by a dysregulated host response to infection. "Sepsis-related hepatic dysfunction is associated with elevated plasma levels of endothelin-1, TNF-α and IL-6." (PMID 28542386, 2017). "Persistently elevated levels of endothelin-1 are associated with myocardial dysfunction in sepsis." (PMID 40041174, 2025). "Interestingly high levels of circulating endothelin-1 have also been linked with sepsis, providing a possible explanation for our results in the pediatric specimens." (PMID 30618794, 2018). "In order to further confirm the involvement of endothelin-1 in sepsis, some researchers performed experiments on septic animals with different medications." (PMID 41153763, 2025). "Several additional biomarkers have been proposed for sepsis prognostication, including serum lactate, endothelin-1, angiopoietin-2, and syndecan-1." (PMID 41153844, 2025). "Endothelin-1 is one of the most potent vasoconstrictors found in the human body and is involved in the pathophysiology of both sepsis and other conditions involving organs that make up the SOFA score." (PMID 41153763, 2025). "Given its involvement in sepsis, septic shock, and liver diseases, endothelin-1 was one of the biomarkers chosen for analysis." (PMID 41153763, 2025). "Endothelin-1 is proven to play an important role in the pathophysiology of sepsis and its complications; elevated plasma levels of ET-1 have been identified in hypotensive septic animals." (PMID 41153763, 2025). "In this review, we aimed to bring together the multiple effects of endothelin-1 described in the literature, more specifically in sepsis and in the systems that make up the SOFA score." (PMID 41153763, 2025). "Endothelin-1 (ET-1), a potent vasoconstrictive peptide released by ECs, exhibits a significant increase in release during sepsis-induced ALI/ARDS following EC activation." (PMID 38664775, 2024). "Data suggest involvement of EDN1 in various infectious disorders (i.e., sepsis and viral or bacterial pneumonia), as well as KD." (PMID 38259468, 2023). "Endotoxin, TNF-α, CSA, and IL-1 upregulate and stimulate the release of the endothelin-1; as a result, ET-1 is released at high levels in sepsis." (PMID 35160072, 2022). "MCs are key players in protection against the vasoconstrictor peptide endothelin 1 (ET-1), which plays an important pathogenetic role in sepsis, skin itch, fibrosis, etc.." (PMID 35159379, 2022). "We determined the plasma levels of interleukin-6 (IL-6; a relatively early biomarker in sepsis) and endothelin-1 (ET-1; a marker of tissue hypoxia) to confirm and characterize the course of pro-inflammatory processes in the animals." (PMID 34815465, 2021). "Several reports have referred to an increase of circulating TGF-β in septic patients and the involvement of Endothelin-1 (ET-1) in the pathogenesis of sepsis." (PMID 31357597, 2019). "Two studies reported that endothelin-1 was significantly elevated in patients with sepsis compared with healthy controls." (PMID 22248019, 2012). "Endothelin-1 is a potent endogenous vasoconstrictor that contributes to renal microcirculatory impairment during endotoxemia and sepsis." (PMID 21760895, 2011). "In conclusion, baseline endothelin-1 and adrenomedullin precursor levels are significantly increased in patients with sepsis and septic shock." (PMID 18080871, 2007). "The potent vasoconstrictor peptide endothelin-1 (ET-1) is released in response to sepsis and endotoxemia." (PMID 16280068, 2005). "Elevated plasma endothelin-1 (ET-1) levels have been reported in patients with sepsis." (PMID 40522976, 2025). "An interesting aspect of the study is represented by the fact that endothelin-1 values and sepsis severity negatively correlated with levels of plasmatic total cholesterol, suggesting that both these biomarkers could predict the outcome of septic children." (PMID 41153763, 2025).
Sepsis (continued). "Overall, although endothelin-1 is heavily involved in fibrosis and chronic liver diseases, there is little evidence to support its implication in sepsis-associated liver dysfunction and/or other acute hepatic conditions." (PMID 41153763, 2025). "They considered that the vasoconstrictor endothelin-1 (ET-1), which is produced predominantly later in the course of sepsis, might have contributed to the pathogenesis." (PMID 41367919, 2025). "It has also been shown that β-blockers (landiolol) may improve sepsis-induced acute lung injury through the pulmonary endothelin-1 system." (PMID 37964887, 2023). "Increased endothelin-1 levels in plasma have also been reported during human sepsis." (PMID 33926378, 2021). "Furthermore, endothelin-1 contributes to CBF impairment by stimulating brain inflammation in sepsis." (PMID 32797301, 2020). "Circulating levels of endothelin-1 are increased in sepsis and correlate with severity of disease." (PMID 18304365, 2008). "PCR confirmed the significant upregulation of the genes including ANXA1, SIPR1, EDN1, and RSAD2 in the neutrophils samples from patients with sepsis-induced immunosuppression (at 3–4 days and/or 6–8 days post sepsis shock) compared with controls (P < .05)." (PMID 33761636, 2021). "In a prospective study targeting patients with sepsis-induced AKI, RAGE levels demonstrated a positive correlation with E-selectin (r = 0.88), endothelin-1 (ET-1) (r = 0.90), and tumor necrosis factor-α (TNF-α) (r = 0.94) levels, while being inversely correlated with NO levels." (PMID 40077627, 2025). "Therefore it is interesting to look at a recent experimental study of sepsis induced respiratory failure in pigs where the authors found lower levels of HBP and lower degree of respiratory failure in the group where endothelin-1 was blocked." (PMID 27007333, 2016). "Endothelin-1 (ET-1) and adrenomedullin (ADM), two endothelium-derived vasoactive peptides, have attracted interest as physiological key mediators in vascular tone regulation in sepsis and cardiovascular disease." (PMID 18080871, 2007).
myocardial infarction (61 papers, 2008 to 2025). Gross necrosis of the myocardium, as a result of interruption of the blood supply to the area, as in coronary thrombosis. "An elevated endothelin-1 (ET-1) level is closely associated with the severity of tissue damage and with the incidence of arrhythmias in cases of acute myocardial infarction." (PMID 37189663, 2023). "High endothelin-1 levels are risk factors for acute myocardial infarction." (PMID 39812046, 2025). "Previous investigations have shown that reduced expression of Edn1 facilitates cardiac recovery following myocardial infarction, a process closely related to the modulation of vascular smooth muscle cell proliferation and immune response after AMI." (PMID 39863867, 2025). "In the heart of rats with myocardial infarction, myofibroblasts found at the site of infarction expressed preproendothelin-1, endothelin-converting enzymes and ETRs." (PMID 36901906, 2023). "In the group of men after myocardial infarction and early post-hospital cardiac rehabilitation, a significantly higher transcriptional activity of the endothelin-1 gene was found." (PMID 35742539, 2022). "In the studied group of patients after myocardial infarction with ST-segment elevation before and after early post-hospital cardiac rehabilitation, a statistically significant increase in the expression of the endothelin-1 gene was observed (p = 0.0234)." (PMID 35742539, 2022). "Transcriptional activity of the endothelin-1 gene in the studied group of patients after myocardial infarction (A) and after early post-hospital cardiac rehabilitation (A1) increased significantly (p = 0.0064)." (PMID 35742539, 2022). "Vascular injury during acute myocardial infarction, and coronary interventional procedure, gives rise to increased endothelin-1 in coronary vasculature." (PMID 32832158, 2020). "Endothelin-1 level in blood circulation is increased in acute myocardial infarction, an acute injurious event of myocardia due to reduced oxygenated blood supply by coronary arteries." (PMID 32832158, 2020). "Serum endothelin-1 is increasingly released in acute myocardial infarction, by necrotic cardiomyocytes." (PMID 32832158, 2020). "A previous study showed that Nico preserved endothelial junctions of VE-cadherin by decreasing endothelin-1 in acute myocardial infarction and reperfusion model." (PMID 30984337, 2019). "Chymase, a mast cell serine protease involved in the generation of multiple cardiovascular factors, such as angiotensin II and endothelin-1 (ET-1), is elevated and participates in tissue degeneration after permanent myocardial infarction (PMI)." (PMID 30233357, 2018). "Endothelin-1 (ET-1) is vasoconstriction peptide produced by the vascular endothelium; increased ET-1 was detected in case of myocardial ischemia and myocardial infarction." (PMID 26539516, 2015). "Increased plasma concentrations of endothelin-1 and big endothelin-1 in acute myocardial infarction." (PMID 23401650, 2013). "Several studies show that endothelin-1 is a predictor for post-myocardial infarction mortality." (PMID 39812046, 2025). "Results and Conclusion: The results show that peptides from the plasma of patients with myocardial infarction promote endothelial cells to release both von Willebrand factor and endothelin-1, increasing vasoconstriction and shifting hemostatic balance toward a prothrombotic state." (PMID 36837440, 2023). "Increased endothelin-1 levels during exercise may contribute to the pathogenesis of acute myocardial infarction that sometimes follows vigorous physical exercise." (PMID 18505546, 2008). "In the conducted study, both in the group of patients after myocardial infarction and early post-hospital cardiac rehabilitation, as well as in the group of people not participating in rehabilitation, significantly increased expression of the endothelin-1 gene was demonstrated." (PMID 35742539, 2022).
myocardial infarction (continued). "The aim of the study was to evaluate the expression of the endothelin-1 gene and its type A receptor, taking into account physical activity (International Physical Activity Questionnaire—IPAQ) among patients with acute myocardial infarction." (PMID 35742539, 2022). "The aim of the study was to evaluate the expression of the endothelin-1 gene (ET-1) and endothelin-1receptor type A (ENDRA), taking into account physical activity (International Physical Activity Questionnaire—IPAQ) among patients with acute myocardial infarction." (PMID 35742539, 2022). "Comparing the results of patients after acute myocardial infarction who did not participate in rehabilitation (B) and after 3 weeks without rehabilitation (B1), a statistically significant increase in the expression of the endothelin-1 gene was observed (p = 0.0268)." (PMID 35742539, 2022).